ROR1 (ROR family WNT receptor 1)
Diseases named in the same sentence as ROR1 in open-access papers (continued):
Sharing a sentence is not in itself a finding about the gene and the disease.
cancer (continued). "Considering that ADCs such as, e.g., brentuximab vedotin or ado-trastuzumab emtansine are nowadays successfully used in the clinic for treating specific cancer entities, the strategy of also using anti-ROR1 ADCs to target ROR1-positive tumors seems especially promising." (PMID 33445713, 2021). "ROR1 signaling genes showed a significant prognostic role in several cancers, including GC." (PMID 34319035, 2021). "Taken together, these observations suggest that ROR1 is indeed expressed on cancer stem cells and might thus be involved in therapy resistance and relapse." (PMID 33445713, 2021). "Moreover, a high level of ROR1 expression in cancer cells appears to be involved in the inhibition of apoptosis and predicts an inferior outcome in primary refractory DLBCL, low-grade FL, and Richter ́s syndrome." (PMID 34090506, 2021). "With several ROR1-targeting therapies currently in development and in phase I clinical trials for other cancers, combination therapy may hold great potential in patients with HGSEC, who currently have limited therapeutic options." (PMID 33494187, 2021). "VLS-101 is an antibody-drug conjugate (ADC) for suppressing ROR1-positive cancers." (PMID 34445128, 2021). "Aberrant expression of ROR1 has been observed in a range of cancers compared to its limited expression in healthy adult tissue, which made it a candidate target for treating these cancers." (PMID 32807831, 2020). "Moreover, ROR1 expression is in line with cancer cell progression, invasion and metastasis, induction of Epithelial-Mesenchymal Transition (EMT), and drug resistance 25–28." (PMID 32695279, 2020). "Consequently, cancer cells expressing ROR1 at higher levels had increased BMI-1 expression and stemness properties, as demonstrated by elevated Nanog, Oct3/4 and Sox2 expression." (PMID 31382410, 2019). "Cancer cells with upregulated ROR1 could be a good opportunity for targeted therapies, where the deleterious effect of GR activation in stress hormone-induced metastasis is prevented by ROR1 inhibition, resulting in cancer cell death." (PMID 31382410, 2019). "In the study, the vaccination with cancer stem cells (CSCs) with high expression of the type I receptor tyrosine kinase-like orphan receptor (ROR1) was evaluated in a murine model for the vaccine's immunogenicity and protective efficacy against epithelial ovarian carcinoma (EOC)." (PMID 31008116, 2019). "ROR1 expression has been associated with mesenchymal/metastatic features of several cancers, but it has not been studied in HCC before." (PMID 30832318, 2019). "Indeed, the prophylactic effects of CSC vaccines in both HO8910 CSC- and ID8 cancer stem-like cell-vaccinated mice were attenuated by ROR1 downregulation in CSCs." (PMID 31008116, 2019). "A ROR1-targeting scFv with a membrane-proximal epitope, R11, which binds to the Kringle domain of ROR1, showed promising in vivo and ex vivo cytotoxicity against ROR1-positive cancer cells." (PMID 31382410, 2019). "Binding of Wnt5a to ROR1 promoted cancer cell survival and metastasis." (PMID 29856777, 2018). "It is possible that differences in glycosylation and trafficking of ROR1 might affect the surface expression of ROR1 in cancer cells." (PMID 29856777, 2018). "Indeed, ROR1 expression was expressed in various human cancers and considered as a biomarker for the prediction of the prognosis of various malignancies." (PMID 29212222, 2017). "Targeting of ROR1 has been evaluated as a novel cancer therapy strategy." (PMID 29212222, 2017). "This discovery also supports our finding that since Beta-1,2,3,4,6-Penta-O-Galloyl-D-Glucopyranose interacts with Ror1 and inhibits its action, this compound could potentially serve as a potent drug for cancer treatment." (PMID 28432357, 2017). "Novel therapeutic strategies to inhibit the scaffold function of ROR1 and thereby attack the cancer’s ‘Achilles heel’ may prove effective against this devastating cancer." (PMID 26725982, 2016).
cancer (continued). "Cell migration and invasion were also suppressed in Wnt5a-, Ror1-, Ror2-, or Fz2-depleted HeLaS3 and A549 cells, suggesting that both cell proliferation and migration capabilities of these cancer cells depend on Wnt5a signaling through its receptors." (PMID 25622531, 2015). "We detected weak or focal ROR1 expression in 4/37 (11%) of tissues judged to be adjacent to cancer." (PMID 25978653, 2015). "Our results and those of others indicate that ROR1 may be an interesting target for cancer immunotherapy." (PMID 26562161, 2015). "This differential expression pattern, low ROR1 expression in adult tissue and high expression in cancer have led investigators to examine the functional advantage conferred to cancer by ROR1 expression and to explore the use of immune-based therapies against ROR1 for targeting cancer cells." (PMID 24752542, 2014). "Much like the physiological functions of ROR1, ROR1 in cancer can have kinase activity-dependent or -independent function, which could be a result of tissue specific expression of co-receptor or effector proteins." (PMID 24752542, 2014). "We also found ROR1 could associate with CK1ε, which was reported to promote the activation of AKT and the survival and proliferation of cancer cells." (PMID 22403610, 2012). "Collectively, our studies indicate that expression of ROR1 is conducive to cancer-cell growth." (PMID 22403610, 2012). "Furthermore, expression of CREB-target genes was reduced in tumors derived from MDA-MB-231 cancer cells than that in tumors silenced for ROR1." (PMID 22403610, 2012). "Our study showed that the cytoplasmic region of Ror1 might be localized in the nucleus in human cancer cell lines." (PMID 20587074, 2010). "The restricted expression of ROR1 in normal adult tissues compared to its frequent overexpression in cancer, specifically in CSCs, makes it an attractive target for therapies aimed at eliminating both CSCs and differentiated cancer cells while minimizing off-target toxicity." (PMID 40869147, 2025). "Furthermore, this combination therapy could potentially increase the specificity of treatment for cancers expressing ROR1." (PMID 39000112, 2024). "If so, then such cancer cells found to express ROR1 by IHC, as noted by others, may not be targeted by agents intended to react with cells bearing surface ROR1 protein." (PMID 39062146, 2024). "Therefore, we hypothesised that ROR1 is a viable and cancer‐specific target and began to target WNT5B through ROR1 inhibition." (PMID 38689429, 2024). "Thus, Matrigel provides cancer cells with a prosurvival microenvironment, and both Ror1 and Rif may mediate this effect by regulating filopodia formation and/or function." (PMID 37703992, 2023). "Moreover, ROR1 has been shown to cancer cell survival and proliferation in various solid tumors." (PMID 37241228, 2023). "ROR1/2 transcript variant sequences, signal peptides for cell surface localisation, and mRNA and transcript variant expression were examined in 34 transcriptomic datasets including 33 cancer types and 54 non-diseased human tissues." (PMID 36289823, 2022). "In this article, we overview recent advances in our understanding of the roles of Ror1 and Ror2-mediated signaling in the development, tissue regeneration and age-related diseases, and discuss their potential to be therapeutic targets for chronic inflammatory diseases and cancers." (PMID 35493090, 2022). "Therefore, we performed an expression analysis in HCC cell lines to gain insight into whether ROR1 is aberrantly expressed in this cancer." (PMID 30832318, 2019). "Finally, by using the pCMVExt-Fc vector, we expressed two challenging proteins, the human ROR1-ED that is involved in cancer progression of a number of blood and solid malignancies and the ligand for the NKG2D activating receptor on the surface of NK cells, ULBP2." (PMID 29997597, 2018).
cancer (continued). "Therefore, we can conclude that Ror1 may be developed as a potential marker for several types of cancer and could be a potential target for stem cell therapy and drug discovery." (PMID 28432357, 2017). "Interestingly, surface ROR1 has been found to be a good target for cancer treatment." (PMID 26945426, 2016). "In conclusion, the present study provides evidence that the dysregulation of ROR1 results from miR-27b-3p downregulation in GC and may promote cancer progression, and the c-Src/STAT3 signaling pathway was involved in miR-27b-3p-ROR1-mediated cell proliferation regulation." (PMID 26576539, 2015). "Targeting ROR1 has been reported to inhibit the EMT process, which plays critical roles in cancer progression and metastasis." (PMID 39739675, 2025). "PBA-0405 (called 2.0405.aF in this manuscript) is a novel, fully human afucosylated anti-ROR1 monoclonal antibody, specifically engineered for optimal induction of antibody-dependent cellular cytotoxicity (ADCC) to improve treatment of cancer." (PMID 41479906, 2025). "For example, monoclonal antibodies have recently been developed to target the ROR1/ROR2 heterodimer and ROR2 homodimer in cancer." (PMID 40667148, 2025). "Effective ROR1 targeting requires elucidating the complex signaling interactions in isolated CSC populations and their impact on disease progression in different cancers." (PMID 40869147, 2025). "The epithelial OC origin of the PDC2 and PDC3 samples was confirmed by the expression of OC-specific markers PAX8 and CD24, epithelial makers MKI67, EPCAM, KRT8 and KRT18 and cancer stem cell markers such as CD44 and ROR1." (PMID 39482470, 2025). "Lately, ROR1 small molecule inhibitors, monoclonal antibodies and CAR T‐cells with ROR1 as target protein have been developed for a variety of different cancer entities." (PMID 41355329, 2025). "Our findings also suggest that the natural small molecule inhibitor PGG can affect ROR1 mediated AKT-GSK3β signaling and reduce cancer survival and metastasis." (PMID 39000112, 2024). "The receptor tyrosine kinase-like orphan receptor 1 (ROR1) plays an essential role in embryogenesis and is overexpressed in many types of malignant tumors." (PMID 38846943, 2024). "ROR1 can serve as a surface receptor for Wnt5a, which can induce ROR1 signaling, leading to activation of ERK1/2, NF-κB, and NRF2, and enhance cancer stemness." (PMID 39062146, 2024). "MEGM DEGs are mainly associated with the topics ‘cancer’, ‘neuro’ and ‘eye & retina’ or two combined topics like ‘cancer and neuro’ (SEMA3C, ROR1, EPHA7, GDNFR) or ‘eye & retina and neuro’ (PRDM8, CRYBG3)." (PMID 39695086, 2024). "Due to the variety of biological interactions, ROR1 represents a target for specific therapies in CLL and other cancers which are reported to express ROR1." (PMID 39551787, 2024). "We also show the unique role of the lncRNA DLEU2/ROR1 pathway in promoting the EMT and cancer stemness behavior via a mechanism closely engaging with TGF-β signaling, which drives EMT and CSC phenotypes via ALDH1 and BMI1 activation." (PMID 38296962, 2024). "In summary, ROR1 is involved in EC pathogenesis, particularly the EMT process, which inhibits cancer metastasis and is highly related to chemoresistance." (PMID 37241228, 2023). "They observed that in the ROR1+MCF7 cells, Wnt5a stimulated the ROR1-dependent cortactin phosphorylation which recruited ARHGEF1 (Rho guanine nucleotide exchange factor 1) to activate RhoA and promote cancer cell migration." (PMID 36873868, 2023). "ROR1 has many pro-survival functions in cancer such as enhancing cell proliferation, epithelial-to-mesenchymal transition (EMT), metastasis, cancer stemness, and therapy resistance." (PMID 38213538, 2023). "Monoclonal antibodies targeting ROR1 and ROR2, which are oncoembryonic antigens found on cancer cells and promote movement, survival, and proliferation, are also being studied." (PMID 37097545, 2023).
cancer (continued). "αROR1-CAR T cells can be activated by ROR1-ScFv conjugation, releasing cytokines including IL-2, IFN-γ, and TNF-α and inducing cytotoxicity in cancer cells." (PMID 35484298, 2022). "Numerous studies have reported cytoplasmic ROR1 expression and contradictory findings for the role of ROR2 in cancer; hence we sought to determine the functionally significant transcript variant that ought to be examined." (PMID 36289823, 2022). "A recent target being explored in patients with CLL is the receptor tyrosine kinase-like orphan receptor 1 (ROR1), that is selectively expressed only on cancer cells." (PMID 35265527, 2022). "We will give a comprehensive overview about the downstream signaling elicited by ROR1 and ROR2, and revisit the current treatment strategies and first promising clinical data for targeting the WNT/ROR pathway in the context of cancer." (PMID 33445713, 2021). "Secondly, ROR1 was shown to upregulate the expression of ATP-dependent translocase ABCB1, a multi-drug efflux pump, and thus facilitate drug export from cancer cells." (PMID 33445713, 2021). "The highly motile and invasive phenotype of the cancer cells has been mainly attributed to the high expression of WNT5A/B and receptor tyrosine kinase-like orphan receptors 1 and 2 (ROR1/2)." (PMID 34911552, 2021). "While different approaches are currently being developed for targeting ROR1, research on ROR2 with regard to its use in cancer therapy is still in its infancy." (PMID 33445713, 2021). "While most studies identified ROR1 as an oncogene, the role of ROR2 in cancer is less clear and has been controversially discussed." (PMID 33445713, 2021). "Receptor tyrosine kinase-like orphan receptor 1 (ROR1) and 2 (ROR2) are receptors for the Wnt5a ligand that have been proposed as potential high-value targets for cancer therapy." (PMID 34774050, 2021). "ROR1 is an oncofetal glycoprotein expressed on CLL, MCL, a variety of malignant tumors, and early-stage B cells but is rarely expressed in normal adult tissues." (PMID 34090506, 2021). "Compared to ROR1, ROR2 has been less investigated as a cancer drug target, likely due to its complex dual role in carcinogenesis." (PMID 34763666, 2021). "We compared the expression of putative cancer stem cell markers (CD24, CD44, CD117, ROR1, and CD133) of HGSC [31134503] at P2 and P8, as well as two HGSOC cell lines." (PMID 32035490, 2020). "We successfully derived FTEC with the expression of the normal stem cell markers (LGR5, SSEA3, and SSEA4), cancer stem cell markers (CD24, CD44, CD117, ROR1, CD133, and ALDH), and characteristics of stem cell." (PMID 32035490, 2020). "Flow cytometry revealed expressions of normal stem cell markers (SSEA3, SSEA4, and LGR5) and cancer stem cell markers (CD24, CD44, CD117, ROR1, and CD133)." (PMID 32035490, 2020). "Another possible link between Hippo-YAP/TAZ and ROR1 signaling is the transcription factor Twist1, which is known to promote EMT in cancer cells." (PMID 31382410, 2019). "This review focuses on the crosstalk between Wnt5a-ROR1 and YAP/TAZ or the BMI-1 signaling network, together with the current advancements in targeted strategies for ROR1-positive cancers." (PMID 31382410, 2019). "One balanced rearrangement studied in detail was shown to result in the fusion of two genes known to be involved in cancer (MACROD2 and ROR1)." (PMID 28655341, 2017). "Receptor tyrosine kinase such as orphan receptor 1 (Ror1), a surface antigen, is a member of the RTK family of Ror, which plays a crucial role in cancers that have high-grade histology." (PMID 28432357, 2017). "This study provides clear evidence that ROR1 is required to sustain caveolae structure in multiple NSCLC cell lines, two other cancer cell lines and COS-7 cells." (PMID 26725982, 2016).
cancer (continued). "Both ROR1 and ROR2 have been linked to the β-catenin independent Wnt signalling pathway, but little is known about the downstream targets of ROR1 and ROR2 in cancer, and their effect on the β-catenin dependent Wnt signalling pathway." (PMID 26515598, 2015). "As the OVCAR3 cell line expressed both ROR1 and ROR2, we were interested to investigate the synergistic effect of ROR1 and ROR2 on cancer cell behaviour." (PMID 26515598, 2015). "However, because some cancer cells have been noted to express Wnt5a, it is conceivable Wnt5a also might serve as an autocrine that can enhance the growth of turmors that co-express ROR1." (PMID 22403610, 2012). "As expression of ROR1 usually occurs in cancer tissue, but not in healthy tissue, this makes ROR1a promising therapeutic target." (PMID 41355329, 2025). "Because ROR1 is not expressed on most normal postnatal tissues, it is a potential target for anti-cancer therapy." (PMID 38408999, 2024). "Receptor tyrosine kinase-like orphan receptor 1 (ROR1) is a cell surface protein overexpressed on various solid and hematological malignancies and minimally expressed on most adult tissues, contributing to cancer stemness." (PMID 38711850, 2024). "The important fact that ROR1 is on the cell surface and is an embryonal antigen not expressed in normal somatic cells strongly supports the use of anti-ROR1 therapies in cancer." (PMID 39551787, 2024). "This drug targets receptor tyrosine kinase-like orphan receptor 1 (ROR1), a cell surface protein expressed on de-differentiated cancer cells, but absent in mature tissues." (PMID 38194201, 2024). "ROR1 is detectable in embryonic tissue, mostly absent in adult tissue and overexpressed in many types of malignant tumors." (PMID 38846943, 2024). "ROR1 is a developmentally restricted type I surface glycoprotein that is expressed on some embryonic cells and neoplastic cells of a variety of different cancers, but virtually not on normal adult tissue." (PMID 39062146, 2024). "The activation of the PI3K-AKT-GSK3β pathway downstream of ROR1 is known to promote EMT by increased expression of mesenchymal markers Snail, Twist1, and MMP9, which all play a significant role in the migration and invasion of cancer." (PMID 38213538, 2023). "We did not observe an association between high-level expression of ROR1 and worse EFS among patients with HR-HER2- or HER2 + cancer subtypes." (PMID 37029329, 2023). "Overexpressions of ROR1, ROR2, and PTK7 have been detected in numerous cancers." (PMID 35504983, 2022). "ROR1 is a receptor tyrosine kinase that is overexpressed in many types of cancers to activate non-canonical WNT signaling pathway." (PMID 36310237, 2022). "Despite its important role in embryogenesis, ROR1 is not expressed in the majority of normal adult tissues and cells, such as B cells, whereas it is overexpressed in many cancer cell types, including CLL and DLBCL-type RS." (PMID 36230566, 2022). "Receptor tyrosine kinase-like orphan receptor 1 (ROR1), an oncofetal protein, is highly expressed on the surfaces of various cancers but not on normal differentiated cells." (PMID 33879198, 2021). "Compared with ROR1, the expression profile of ROR2 in cancer is much more heterogeneous." (PMID 33445713, 2021). "Some genes, which appeared to be virtually switched off in B4GALNT2-expressing cells, are involved in the basic properties of cancer cells, such as stemness (SOX2, ROR1), epithelial to mesenchymal transition (EMT) (NID1, ALX1), and growth (FAM110B, PEG10, MID2)." (PMID 32290493, 2020). "ROR1 and ROR2 are receptor tyrosine kinases with altered expression in a range of cancers." (PMID 32807831, 2020). "We found ROR-1 was indeed highly expressed in human HO8910 CSCs and in ID8 cancer stem-like cells." (PMID 31008116, 2019). "The Wnt5a-ROR1-dependent upregulation of YAP/TAZ and BMI-1 points toward a new positive feedback loop that may play an important role in mediating cancer stemness, tumorigenesis and drug resistance." (PMID 31382410, 2019).